LTA (lymphotoxin alpha)
Description:
Cytokine that in its homotrimeric form binds to TNFRSF1A/TNFR1, TNFRSF1B/TNFBR and TNFRSF14/HVEM. In its heterotrimeric form with LTB binds to TNFRSF3/LTBR. Lymphotoxin is produced by lymphocytes and is cytotoxic for a wide range of tumor cells in vitro and in vivo.
Synonyms: TNFB; TNFSF1; LT; TNLG1E
Tractability: Antibody: a drug acting on it is in phase 2 or 3 trials; its Gene Ontology location is reachable by antibodies, with high confidence; UniProt places it where antibodies can reach, with medium confidence; UniProt predicts a signal peptide or a membrane-spanning region. PROTAC: a small molecule that binds it is known. Other modalities: a drug acting on it is in phase 2 or 3 trials.
Target class: Secreted protein
Safety:
Unwanted effects reported when the protein is acted on. In parentheses: how it was acted on, where the effect was seen, and who reports it.
hypersensitivity (source: ClinPGx)
Gene: Protein-coding gene on chromosome 6 (31,572,054 to 31,574,324, forward strand). Ensembl gene ENSG00000226979.
Subcellular location: Secreted; Membrane
Pathways (Reactome):
Immune System: TNF receptor superfamily (TNFSF) members mediating non-canonical NF-kB pathway; TNFR2 non-canonical NF-kB pathway; TNFs bind their physiological receptors
Gene Ontology:
Molecular function: protein binding; cytokine activity; signaling receptor binding; tumor necrosis factor receptor binding
Biological process: activation of NF-kappaB-inducing kinase activity; apoptotic process; cell surface receptor signaling pathway; cell-cell signaling; dendritic cell homeostasis; immune response; positive regulation of canonical NF-kappaB signal transduction; positive regulation of extrinsic apoptotic signaling pathway; regulation of necroptotic process; regulation of type I interferon production; signal transduction; cell communication; negative regulation of fibroblast proliferation; positive regulation of apoptotic process; positive regulation of glial cell proliferation; response to hypoxia; response to lipopolysaccharide; response to nutrient; response to xenobiotic stimulus; signaling
Cellular component: plasma membrane; tumor necrosis factor receptor superfamily complex; extracellular region; membrane
Genetic constraint (gnomAD): Loss-of-function variants: 6 observed, 15.57 expected, observed/expected ratio (o/e) 0.39, 90% interval 0.21 to 0.76. The upper end of that interval is the gene's LOEUF score, 0.76, which puts it in group 3 of 6, group 1 being the genes least tolerant of losing a copy. Missense variants: 173 observed, 256.57 expected, observed/expected ratio (o/e) 0.67, 90% interval 0.6 to 0.76. Synonymous variants: 87 observed, 112.1 expected, observed/expected ratio (o/e) 0.78, 90% interval 0.65 to 0.93.
Homologues: Orthologues: chimpanzee LTA (99% identical), macaque LTA (98% identical), pig LTA (78% identical), rat Lta (73% identical), mouse Lta (72% identical), rabbit LTA (72% identical), guinea pig LTA (65% identical), tropical clawed frog lta (31% identical), zebrafish tnfa (27% identical), zebrafish tnfb (26% identical). Paralogues in human: TNF (29% identical), LTB (27% identical), TNFSF15 (26% identical), FASLG (25% identical), TNFSF14 (22% identical), TNFSF11 (19% identical), TNFSF10 (18% identical), CD40LG (16% identical).
Diseases named in the same sentence as LTA in open-access papers:
LTA is named in the same sentence as 269 diseases in open-access papers, as found by Europe PMC text mining. Sharing a sentence is not in itself a finding about the gene and the disease. The quoted sentences say what the papers report.
COVID-19 (31 papers, 2021 to 2026). A disease caused by infection with severe acute respiratory syndrome coronavirus 2. "In contrast, TNF-β/LTα levels were lower in COVID-19 patients (0.16 ± 0.04 pg/mL) than controls (0.39 ± 0.06 pg/mL, p < 0.001)." (PMID 36851770, 2023). "An increased expression of CCL3, CCL4, CSF2, IL1B, and LTA was found in the revaccinated groups (groups 5 and 6), which in fact experienced decreased expression in severe COVID-19 patients." (PMID 36225326, 2022). "Among these proteins, KRT19, TOP2B, AREG, HGF, CKAP4, ITGB6, and NCF2 had a higher expression (> twofold) in plasma samples of severe compared to moderate COVID-19 patients, whereas CLEC4C and LTA were among the few proteins that were expressed at lower levels in severe patients." (PMID 36829233, 2023). "In the critical COVID-19 group, the heatmap and volcano plot even showed that the levels of some circulating cytokines were marginally lower in patients with asthma than those without asthma, particularly on THPO, LTα, and TGFα." (PMID 34238349, 2021).
rheumatoid arthritis (23 papers, 2012 to 2025). A chronic, systemic autoimmune disorder characterized by inflammation in the synovial membranes and articular surfaces. "Pateclizumab (MLTA3698A) is a humanized mAb against lymphotoxin α (LTα), a transiently expressed cytokine on activated B and T cells (Th1, Th17), which are implicated in rheumatoid arthritis (RA) pathogenesis." (PMID 22225620, 2012). "Tumor necrosis factor (TNF) and, possibly, lymphotoxin alpha (LTα) signaling contribute to inflammation and rheumatoid arthritis (RA) pathogenesis." (PMID 25359150, 2014). "Recent studies suggest that LTα is closely related to immunoinflammatory-related diseases, such as rheumatoid arthritis (RA) and graft-versus-host disease (GVHD)." (PMID 33441130, 2021). "Patient TN2 was undergoing treatment with soluble tumor necrosis factor-alpha (TNF-α)/lymphotoxin-alpha (LT-α) receptor for therapy of rheumatoid arthritis with Sjögren syndrome at the time of collection; IFI27 expression could be indirectly induced by this treatment." (PMID 27100186, 2016). "Not surprising in view of its ability to interact with TNFR2, LTα2β is inhibited by Etanercept, which is approved for the treatment of rheumatoid arthritis and also inhibits TNF and LTα." (PMID 33824270, 2021). "Therefore, our results support the hypothesis that blocking LTα may serve as a viable target for JIA treatment, echoing previous suggestions for rheumatoid arthritis management." (PMID 39175752, 2024).
autoimmune disease (16 papers, 2012 to 2025). A disorder resulting from loss of function or tissue destruction of an organ or multiple organs, arising from humoral or cellular immune responses of the individual to their own tissue constituents. "The lymphotoxin-alpha (LTα) and lymphotoxin-beta (LTβ) pathways have been associated with the presence of ectopic lymphoid structures at the sites of chronic inflammation in several autoimmune diseases." (PMID 24286296, 2013). "Increased levels of LTα and LTβ molecules, and their activation, have been associated with the presence of ectopic lymphoid structures at sites of chronic inflammation in several autoimmune diseases." (PMID 24286296, 2013). "Increases in LTα, a member of the TNF family, in serum and salivary glands has been associated with early stages of the autoimmune disease in both pSS patients and IL14α-TG mice." (PMID 26365984, 2015). "Since biologics targeting TNF (or both TNF and soluble LTα) are used for treatment of autoimmune diseases, it is of great importance to understand all functions mediated by the ligands of TNF/LT system in normal physiology." (PMID 35741098, 2022).
melanoma (16 papers, 2014 to 2025). A malignant, usually aggressive tumor composed of atypical, neoplastic melanocytes. "For instance, inoculation of B16F10 melanoma cells into LTα-deficient mice resulted in accelerated lung metastasis as compared with littermate control mice, presumably, due to impaired natural killer (NK) cell migration to the lungs." (PMID 33917839, 2021). "Furthermore, endogenous CD8+ T cells specific for the melanoma-associated antigen TRP-2 were detected by in situ tetramer staining only within tumors of LTα−/− animals in which TLSs had been induced." (PMID 29312327, 2017). "For instance, genetic knockout of LTα leads to enhanced tumor growth and elevates the risk of metastasis in C57BL/6 mice inoculated with B16F10 melanoma as compared with littermate control mice." (PMID 33917839, 2021). "An anti-disialoganglioside 2 (GD2) antibody fused to LTα has promoted anti-tumor specific T cell responses in LTα-/- mice bearing GD2-expressing B16 melanoma." (PMID 34276690, 2021). "LTA+ and IL-10+ B cell subpopulations were mainly found in the intratumoral stromal septa and the peritumoral stroma of melanoma metastases." (PMID 34359321, 2021). "Targeting of an antibody-LTα fusion protein directly to mouse melanomas resulted in neogenesis of TLS-like lymphoid aggregates including PNAd+ HEVs." (PMID 29312327, 2017). "However, at least in melanoma, hepatocellular and colon cancer, it seems that the presence of LTα or LTβ within the tumor slows growth." (PMID 24762633, 2014). "Overall, 89%, 92%, 82%, and 50% of patients failed to display detectable serum levels of BAFF/TNFSF13B, CX3CL1, LTα, and CCL21 (defined as < 2 pg/ml, < 0.5 pg/ml, < 1 pg/ml and <7 pg/ml for the respective analytes) amongst an initial cohort of 78 melanoma patients evaluated." (PMID 37435077, 2023). "While previous studies had demonstrated the ability of B16 melanoma tumors to foster T cell priming in the absence of SLOs in LTα−/− mice, the study by Schrama and colleagues was one of the first studies to specifically associate this capability with the presence of intratumoral TLSs." (PMID 29312327, 2017).
asthma (12 papers, 2007 to 2025). "Polymorphisms in the proinflammatory cytokine genes tumor necrosis factor-α (TNF) and lymphotoxin-α (LTA, also called TNF-β) have been associated with asthma and atopy in some studies." (PMID 17450233, 2007). "In depth analyses of the asthma associated genes encoding for lymphotoxin alpha (LTA) and tumor necrosis factor (TNF) on chromosome 6p21.3, showed that differentially methylated CpG sites are enriched in the promoter region (5′UTR, 1st exon) and differ according to lymphoid versus myeloid lineages." (PMID 22848472, 2012).
depression (8 papers, 2016 to 2025). "Similarly, human studies have consistently found that circulating levels of at least 15 markers such as CRP, IL-2, IL-6, CCL3, TNF-α, and TNF-β (also known as Lymphotoxin-alpha) were increased in patients with depression." (PMID 41010394, 2025).
influenza (8 papers, 2009 to 2025). An acute viral infection of the respiratory tract, occurring in isolated cases, in epidemics, or in pandemics; it is caused by serologically different strains of viruses (influenzaviruses) designated A, B, and C, has a 3-day incubation period, and usually lasts for 3 to 10 days. "Similarly, LTα is not fully required for formation of iBALT, as lymphocytic aggregates form in influenza-infected Lta−/− mice and lymphoid chemokines CXCL13 and CCL21 are detectable." (PMID 27872626, 2016). "Indeed, mice deficient in both LTα and TNF express CXCL13 in the lung in response to influenza infection, despite no expression in SLOs." (PMID 40884054, 2025). "LTα‐deficient mice are able to generate delayed protective immune responses to influenza and murine gamma herpesvirus 68 infections, suggesting functional TLS formation in the absence of LT/LTβR signaling." (PMID 40884054, 2025).
malaria (8 papers, 2012 to 2023). Malaria is a serious and sometimes fatal disease caused by a parasite that commonly infects a certain type of mosquito which feeds on humans. "In humans, polymorphism within the lymphotoxin alpha (LTα) has been linked to several diseases, such as leprosy and malaria." (PMID 36693052, 2023). "The TNF and LTA genes are implicated in the host defense and pathogeneses of severe malaria." (PMID 22615793, 2012). "Noticeably, the 1-LOD drop area contained only five genes, and among them, TNF, LTA, and NCR3 have been associated with mild malaria or parasitaemia." (PMID 24884991, 2014). "Variations in several host genes (HBB, IL4, IL12, TNF, LTA, NCR3 and FCGR2A) have been reported to be associated with malaria outcome." (PMID 24066864, 2013). "It should be noted that some of these association signals could result from genotypic combinations with neighboring genes, namely lymphotoxin-alpha (LTA) and more detailed analysis of this region is needed to discern the involvement of TNF in human severe malaria." (PMID 31417551, 2019).
migraine (8 papers, 2008 to 2025). "Research has also shown that lymphotoxin alpha (or tumor necrosis factor-beta) and α-fodrin are among the seven-upregulated genes in migraine with aura, compared with healthy controls." (PMID 35896985, 2022).
psoriasis (8 papers, 2016 to 2025). An autoimmune condition characterized by red, well-delineated plaques with silvery scales that are usually on the extensor surfaces and scalp. "Polymorphism in the genes coding for IL-19, IL-20 and LTA (lymphotoxin alpha) have been associated with both PPP and psoriasis." (PMID 27152848, 2016). "Furthermore, the inflammatory indicators found to be upregulated in psoriasis MCs, such as ATF4, CXCL12, LTA, TACR1, TLR4, and CTSB, interestingly share IL-1β as a common modulator." (PMID 37681909, 2023).
schizophrenia (8 papers, 2015 to 2024). A major psychotic disorder characterized by abnormalities in the perception or expression of reality. "Limited research has assessed associations between schizophrenia and genetic variants of the ankyrin repeat and kinase domain containing 1 (ANKK1) and lymphotoxin-alpha (LTA) genes among individuals of Middle Eastern ancestry." (PMID 26114114, 2015).
atherosclerosis (7 papers, 2011 to 2025). A disease characterized by the build-up of fatty material and calcium deposition in the arterial wall resulting in partial or complete occlusion of the arterial lumen. "In vitro experiments demonstrate LTα upregulates adhesion molecule expression, and LTα deletion reduces atherosclerosis in mice." (PMID 23704873, 2013). "Notably, these correlations might suggest a link between the metabolome and protein markers related to immune signalling (LTα, CD6, CCL21, SELE), energy balance and metabolism-related hormones (IGFBP1, SHGB, ADM, leptin, and STC1), and atherosclerosis/thrombosis inhibitor (PAI1)." (PMID 39154540, 2024).
leprosy (7 papers, 2009 to 2023). Leprosy is a chronic infectious disease affecting primarily the skin and peripheral nervous system. "Various genes (HLA-DR, PARK2/PACRG, LTA, TLRs, etc.)and genomic regions (10p13, 6q25–26, 6p21, 17q11–q21, 20p13, etc.)of human genome have been associated with or linked to leprosy (or a particular clinical form of leprosy) by candidate gene association studies or genome-wide linkage analysis." (PMID 22238647, 2012). "LTα and TNFα have been shown to play independent roles in the evolution of the granulomatous response in experimental leprosy because of their distinctive roles in the recruitment of lymphocytes." (PMID 29201923, 2017). "It has been reported that the HLA lymphotoxin-alpha (LTA)+80 locus within the 6p21 chromosomal region is a major risk factor for early-onset (i.e., < 16 years old) leprosy." (PMID 20003324, 2009). "Indeed, a strong host genetic contribution to leprosy susceptibility has been well established through the identification of leprosy susceptibility genes by both positional cloning (PARK2, LTA, HLA-C, MRC1) and candidate gene approaches (e.g. TLR1, TNF, CUBN and NEBL)." (PMID 28793313, 2017). "Summary of associations between genes of innate immune response MICA, MICB, KIR, TNF, LTA, BAT1, IFNG, and leprosy." (PMID 26793196, 2015).
Sepsis (7 papers, 2006 to 2024). Sepsis is defined as life-threatening organ dysfunction caused by a dysregulated host response to infection. "Ten SNPs in TNF, LTA, TNFRSF1A and TNFRSF1B were genotyped in samples of patients with severe sepsis (n = 432), sepsis (n = 384) and healthy controls (n = 624)." (PMID 23029405, 2012). "Considering the important role of TNF-α, LT-α, TNFR1 and TNFR2 in the pathogenesis of severe sepsis, we hypothesized that genetic variation in TNF, LTA, TNFRSF1A and TNFRSF1B might be associated with susceptibility to and outcomes from severe sepsis in Chinese Han population." (PMID 23029405, 2012).
Arthritis (6 papers, 2006 to 2023). Inflammation of a joint. "A mouse-specific depleting mAb targeting surface LTα has been shown to ameliorate inflammation and arthritis in murine models of disease." (PMID 22225620, 2012). "This may be of particular importance due to the pro-inflammatory role of LTα that was demonstrated in different mouse models of inflammatory diseases, including experimental arthritis and EAE." (PMID 34305946, 2021).
Cognitive impairment (6 papers, 2021 to 2025). Abnormal cognition is characterized by deficits in thinking, reasoning, or remembering. "In addition, lymphotoxin alpha (LTα), which has an important function in stimulating cellular immunity, was lower in women with cognitive impairment." (PMID 37901041, 2023).
non-Hodgkin lymphoma (6 papers, 2013 to 2022). Distinct from Hodgkin lymphoma both morphologically and biologically, non-Hodgkin lymphoma (NHL) is characterized by the absence of Reed-Sternberg cells, can occur at any age, and usually presents as a localized or generalized lymphadenopathy associated with fever and weight loss. "Increased expression of LTα has been demonstrated in several types of cancer, including Burkitt's lymphoma, and LTα polymorphisms are associated with increased risk of non-Hodgkin's lymphoma." (PMID 25915535, 2015). "Intriguingly, we also found that rs909253, which is predicted to alter the binding of SPIB, is associated with increased risk for myocardial infarction, non-Hodgkin lymphoma, and psoriatic arthritis, suggesting that the onset of these complex diseases may be due in part to LTα expression levels." (PMID 31791241, 2019).
lung fibrosis (5 papers, 2012 to 2025). "CRP (rho:0.449, p=0.009), LTα (rho:0.487, p=0.004), and IL-6 (rho: 0.400, p=0.021), all of which are associated with lung fibrosis were found to correlate with Gal9 levels." (PMID 40977722, 2025).
lymphoma (5 papers, 2014 to 2024). A malignant (clonal) proliferation of B- lymphocytes or T- lymphocytes which involves the lymph nodes, bone marrow and/or extranodal sites. "Inhibition of LTβR signaling by anti- LTβR antibody or knockdown of LTα impaired cell interaction between lymphoma cell and stromal cell, potentially by disrupting production of CCL19 and CCL21 by stromal cells which are ligands for CCR7." (PMID 25211095, 2014). "To determine whether lymphoma T cells express LTα in situ, we performed immunohistochemical (IHC) staining of skin biopsy specimens obtained from 10 patients diagnosed with CTCL." (PMID 25915535, 2015). "To address this question, we validated eight plasma proteins (IL-17A, F5, FLT4, SFTPB, and GNPTG in lymphoma, TNFSF12, CCL3, and KIT in NSCLC) for response prediction and three plasma proteins (IL36G, SERPINC1, and LTA) for relapse monitoring." (PMID 38349411, 2024). "The expression of the LTβR in BECs and its ligands Ltα, Ltβ, and Tnfsf14 (LIGHT) in DCs remained unchanged in lymphoma." (PMID 34706240, 2021).